MGMT (O-6-methylguanine-DNA methyltransferase)
Diseases named in the same sentence as MGMT in open-access papers (continued):
Sharing a sentence is not in itself a finding about the gene and the disease.
melanoma (continued). "Consequently, we aimed here to investigate comprehensively MGMT promoter methylation and MGMT immunohistochemistry in brain metastases derived from lung, breast and renal cell carcinomas as well as from malignant melanomas." (PMID 19274096, 2009). "We undertook a phase II trial of LM and TMZ (LM/TMZ) to establish whether inactivation of MGMT by the former might increase the efficacy of TMZ in patients with advanced melanoma." (PMID 19367283, 2009). "This shows that in melanoma cell lines MGMT is a decisive marker of alkylating drug resistance." (PMID 19127257, 2009). "Resistance to cisplatin in melanoma may be related to sequestration of the drug in melanosomes, and resistance to alkylating agents may be mediated by expression of MGMT, which opposes their action." (PMID 19949544, 2009). "Because of this, and the high frequency of MMR-defective melanoma cell line (1 out of 11), down-regulation or impaired MMR might be considered (together with up-regulation of MGMT) a cause of acquired resistance to TMZ and other methylating drugs." (PMID 19127257, 2009). "Improving response rates in melanoma may rest on modulating these and other factors, in combination with the suppression of MGMT activity." (PMID 19367283, 2009). "MGMT-immunoreactivity and evidence of promoter methylation in 9% of the samples may reflect differences in the methylation status of the MGMT promoter in tumor cell subpopulations as it is reported for malignant melanoma." (PMID 19274096, 2009). "MGMT-immunoreactivity was assessed of 285 brain metastases using a tissue microarray (77 lung carcinomas, 62 breast carcinomas, 42 renal cell carcinomas, 104 malignant melanomas)." (PMID 19274096, 2009). "In view of the role of MGMT in the defence against O6MeG one might anticipate that MGMT determines the clinical outcome in melanoma therapy with methylating drugs." (PMID 19127257, 2009). "This could help to determine to what extent MGMT has a clinical impact as a drug resistance factor in malignant melanoma." (PMID 14562026, 2003). "We observed an inverse relationship between MGMT expression and clinical response to DTIC-based chemotherapy in patients with metastatic melanoma (P=0.05), indicating that MGMT is a factor that contributes to drug resistance against DTIC-based chemotherapy in melanoma." (PMID 14562026, 2003). "Different metastases in the same patient also frequently expressed different levels of MGMT, which may explain why some melanoma patients obtain only a partial response to chemotherapy even though they have a low MGMT expression in the excised tumours." (PMID 14562026, 2003). "In addition, a significant association between longer survival times, following locoregional melphalan chemotherapy in stage IIID melanoma patients with locoregional pelvic metastases, and a 14% cut-off value for O6-methylguanine-DNA methyltransferase (MGMT) promoter methylation has been reported." (PMID 33562337, 2021). "The DNA repair gene MGMT (O-6-methylguanine-DNA-methyltransferase) is silenced in approximately 20% of melanoma, and its inactivation corresponds with declines in the ability to repair DNA which may promote mutagenesis and potentiate the response to DNA-damaging chemotherapy." (PMID 19949544, 2009). "Therefore, we assessed MGMT promoter methylation of various brain metastases including those derived from lung (n = 91), breast (n = 72) kidney (n = 49) and from malignant melanomas (n = 113) by methylation-specific polymerase chain reaction (MS-PCR) and MGMT immunoreactivity." (PMID 19274096, 2009).
melanoma (continued). "Thus, lower MGMT activities in PBMCs have been associated with increased haematological toxicity in a phase II study of temozolomide in adult melanoma patients and inactivation of MGMT was correlated with haematological toxicity in a phase I study of temozolomide." (PMID 16136028, 2005). "No polymorphisms were found in exons 2 and 4 of the MGMT gene in our melanoma patients." (PMID 14562026, 2003). "In the present study, MGMT expression has been analysed in additional tumour samples to further investigate whether MGMT may be a drug resistance factor to DTIC-based chemotherapy in melanoma." (PMID 14562026, 2003). "Single nucleotide polymorphisms in the MGMT gene can have effects on the MGMT activity or on sensitivity to the MGMT inhibitor O6-benzylguanine (O6-BG) and might therefore have an effect on clinical response to DTIC-based chemotherapy in melanoma." (PMID 14562026, 2003). "vMF increased the sensitivity of melanoma (MM) to TMZ in vitro and in vivo through downregulating MGMT and promoting the TMZ induced DNA damage in MM." (PMID 39873425, 2025). "It was reported that the tumour suppressor cytokine IL‐24 is downregulated during melanoma progression, and supplementing IL‐24 has been shown to reverse melanoma resistance to TMZ by downregulating MGMT." (PMID 39873425, 2025). "In melanoma, DNMTs can remove methyl groups from DNA and restore the activity of tumor suppressor genes, such as p16INK4a, RASSF1A, and MGMT, which are frequently repressed in melanoma." (PMID 39199614, 2024). "Overall, our results demonstrate that MGMT expression regulates radioresponse in GBM, GSC, and melanoma, implying a role for MGMT as a target for radiosensitization." (PMID 38811596, 2024). "With depletion of MGMT, A375 and SK-MEL-28 exhibited sensitivities to DTIC demonstrating that MGMT was involved in the DTIC resistance in the two melanoma cell lines." (PMID 37024907, 2023). "They observed that the incidence of TSG hypermethylation increased during tumor progression and that MGMT, RASSF1A, and DAPK hypermethylation were significantly lower in primary melanomas compared to metastatic ones." (PMID 34944843, 2021). "When MGMT-low human melanoma cells (1205Lu and HS294T) were treated with TMZ for over two months, MGMT was upregulated, and cells became resistant." (PMID 32899791, 2020). "In previous studies, MGMT status was shown to be related to the occurrence and invasion of non-small cell lung cancer (NSCLC), melanoma, malignant glioma, esophageal cancer, and prostate cancer." (PMID 32141507, 2020). "Accordingly, pharmacological depletion or inhibition of MGMT has demonstrated enhanced TMZ sensitivity in pre-clinical studies on GBM and melanoma." (PMID 32899791, 2020). "Our study reveals rare expression of MGMT as a stochastically pre-existing, key determinant of TMZ resistance in melanoma cell lines." (PMID 30274152, 2018). "Altogether, these data reveal stochastic expression of MGMT as a pre-existing, key determinant of TMZ resistance in melanoma cell lines." (PMID 30274152, 2018). "TMZ is in clinical use for melanoma, but objective response rates are low, even when TMZ is combined with O6-benzylguanine (O6BG), a potent MGMT inhibitor." (PMID 30274152, 2018). "A follow-up study investigated the methylation of RARB2, MGMT, DAPK, and RASSF1A in 20 primary melanomas, 86 metastatic melanoma, and 15 cell lines." (PMID 28396701, 2017). "Previous studies in melanoma and surrogate samples have revealed epigenetic markers based on methylation patterns of LINE-1, RASSF1A, TSLC1,and MGMT." (PMID 26106605, 2015). "Similar findings were reported for the other MGMT pseudosubstrate, lomeguatrib, ones administered in combination with TMZ for treatment of melanoma." (PMID 25460932, 2014).
melanoma (continued). "Given the results of the xenograft studies with melanoma, and now breast cancer, it seems reasonable to speculate that the greatest benefit from PaTrin-2-mediated inactivation of MGMT might be seen in tumours with the highest levels of MGMT expression and inherent resistance to temozolomide." (PMID 16278661, 2005). "Another MGMT inhibitor, O6-4-bromothenyl-guanine (4BTG) enhanced the antitumour effect of TMZ in human melanoma xenografts." (PMID 14562026, 2003). "At the same time, we found that the ERK inhibitor vMF downregulates the expression of MGMT in the A375 and Sk‐MEL28 melanoma cell lines, indicating that the ERK inhibitor vMF may increase TMZ cytotoxicity in melanoma cells." (PMID 39873425, 2025). "Our experimental findings suggest that TMZ promotes the transcription of MGMT by activating the ERK signalling pathway and that the use of an ERK pathway inhibitor effectively increases the sensitivity of melanoma cell lines to TMZ both in vivo and in vitro by downregulating MGMT levels." (PMID 39873425, 2025). "We found that the levels of MGMT and p‐ERK1/2 were positively correlated in melanoma tissues." (PMID 39873425, 2025). "Herein, we evaluated whether MGMT expression affected the radioresponse of human GBM, GBM stem-like cells (GSCs), and melanoma." (PMID 38811596, 2024). "Thus, our cell lines were classified as MGMT-producing (GBM [ACPK1], GSCs [GBMJ1], and melanoma [A375 and MM415]) or non-MGMT-producing (GBM [OSU61], GSCs [NSC11, and melanoma [WM852 and WM266-4])." (PMID 38811596, 2024). "In this study, we found that PA reduced MGMT protein levels in melanoma cells via destabilization of MGMT rather than transcriptional regulation, and acted synergistically with DTIC to augment DNA damages and apoptosis in melanoma cells." (PMID 37024907, 2023). "The data suggested that PA-mediated transcription alteration was not involved in the regulation of MGMT in the two melanoma cell lines." (PMID 37024907, 2023). "Similarly, the most hypermethylated gene in melanoma cell lines was RASSF1A (80%), followed by RARRES2 (53%) and MGMT (27%)." (PMID 34441278, 2021). "Moreover, the infection of miR-650 mimics in melanoma cells also inhibited the cell viability of melanoma cells with DTIC treatment, which was also observed in the MGMT expressing cells." (PMID 33816296, 2021). "For instance, high levels of promoter methylation correlated with active expression of EBF3, MGMT, HOXD12 and GATA4 in melanoma, indicating other factors may affect the relations of DNA methylation with transcriptional activity." (PMID 34013637, 2021). "TMZ has been combined with inhibitors that target not only MGMT, NF-κB, and Notch signaling but also AKT, mTOR signaling, autophagy, and glutaminase-mediated glutamine metabolism, all of which significantly enhanced TMZ cytotoxicity in melanoma cells." (PMID 32899791, 2020). "Therefore, to understand MGMT-independent acquired resistance mechanisms to TMZ, we selected melanoma cells that were initially sensitive and became resistant later." (PMID 32899791, 2020). "Lack of MGMT stimulation by TMZ is further supported by a study showing that TMZ exposure of melanoma cells in vitro does not alter MGMT mRNA expression." (PMID 30274152, 2018). "Altogether, these results further established anti-melanoma activity of topical NEO412, although higher dosages seemed to be required in the case of MGMT-positive tumors; further, the activity of distally applied NEO412 pointed to a potential systemic component of this effect." (PMID 30651933, 2018). "Consistent with earlier in vitro studies, we found that TMZ combined with O6BG was hugely potent in all our melanoma cell lines, irrespective of their MGMT status." (PMID 30274152, 2018).
melanoma (continued). "Our study provides proof of principle that NEO412 is effective against melanomas in vitro and in vivo, in both MGMT-positive and -negative tumors." (PMID 30651933, 2018). "In a human melanoma cell line panel we assessed levels and activation of IGF-1R and its effectors AKT and ERKs, and expression of O6-methylguanine-DNA methyltransferase (MGMT) that removes the most toxic TMZ-induced DNA adduct, O6-methyguanine (O6-meG; )." (PMID 26497996, 2015). "We also detected DNA methylation differences between acral and nonacral melanoma subtypes at MGMT and TERT bodies." (PMID 26106605, 2015). "O6-methylguanine-DNA-methyltransferase expression was very low in all the melanoma samples tested, irrespective of the MGMT promoter methylation status determined or clinical outcome." (PMID 20736948, 2010). "In conclusion, the data reveal that MGMT promoter methylation does not correlate with clinical outcome of TMZ treatment in stage IV melanoma." (PMID 20736948, 2010). "In contrast MGMT promoter methylation and lack of MGMT reactivity ranged between 67% (2 of 3 breast cancer) and 32% (11 of 34 melanomas)." (PMID 19274096, 2009). "3+ samples were most frequent in breast and lung carcinoma metastases (46.8% and 42.6% respectively) whereas more than 45% of renal cell carcinoma and melanoma brain metastases were MGMT negative." (PMID 19274096, 2009). "The use of such inhibitors may help to determine the role of MGMT in resistance to DTIC-based chemotherapy and may be used to improve the clinical results in treatment of malignant melanoma." (PMID 14562026, 2003). "This further echoed our experimental results that the transcription of MGMT was not high in melanoma in the absence of drugs but could be strengthened compensatively after exposure to TMZ." (PMID 39873425, 2025). "BRO melanoma cells did not express MGMT; therefore, their resistance to alkylating agents could be associated with other mechanisms." (PMID 36533319, 2023). "Moreover, further study showed that miR-650 overexpression alleviated MGMT-induced DTIC resistance in melanoma by increasing cell apoptosis, which indicated that miR-650 was a novel biomarker of great value for the evaluation of melanoma." (PMID 35331235, 2022). "MGMT plays a central role in preventing normal cells from transforming into tumor cells and also protects tumor cells from the cytotoxic effects of chemotherapy with alkylating agents, such as temozolomide (TMZ) and dacarbazine (DTIC), widely used in treating melanoma and glioblastoma." (PMID 34944843, 2021). "Since hypermethylation at the promoter region of tumor suppressor genes, e.g., RARB2, TFPI2, RASSF1A, MGMT, and PTEN, helped to distinguish melanoma patients from healthy individuals, epigenetic changes in cfDNA may also serve as diagnostic markers in melanoma." (PMID 34575876, 2021). "A negative correlation between miR-650 and MGMT was also observed in melanoma tissues." (PMID 33816296, 2021). "Notably, MGMT is not an exclusive player involved in melanoma cell death induced by alkylating drugs." (PMID 29747595, 2018). "We have demonstrated that NEO412 exhibited its cytotoxicity against melanoma cells in vivo when the agent is applied to the skin directly above the tumor as well as at distant sites and the agent is effective in a dose dependent manner in TMZ resistant cells (MGMT positive)." (PMID 30651933, 2018). "To gain insight into the mechanism by which these melanoma cells might switch their MGMT status from negative to positive, we investigated control of promoter activity by methylation." (PMID 30274152, 2018). "Although MGMT inhibitors are not routinely applied in melanoma therapy, the conclusions can be translated to the therapeutic situation as TMZ/DTIC is being used daily, which is supposed to cause a depletion of MGMT in tumor cells and MGMT in melanoma has been shown to be predictive of outcome." (PMID 25557167, 2014).
melanoma (continued). "Also recent experimental data in human melanoma cell lines have confirmed the presence of a close correlation between MGMT activity and the level of resistance to TMZ and FM, although a wide variability in MGMT activity among different cell lines was noted." (PMID 21067582, 2010). "Similar to malignant gliomas, melanomas express, compared to other cancers, quite low levels of MGMT, which might explain why melanomas respond to the methylating drugs DTIC and TMZ, but not to many other anticancer drugs." (PMID 19127257, 2009). "Despite the effects of the MGMT inactivator on enhancing bone marrow toxicity, we failed to see a similar effect on melanomas, suggesting that tolerance of damage and/or failure of downstream elements required for cytotoxicity have greater importance in melanoma cells." (PMID 19367282, 2009). "Thus, the pretreatment levels of MGMT in biopsies of cutaneous tumours were not related to the outcome whereas a later study showed that MGMT expression in melanoma metastases was related to the clinical response of the patients to DTIC-based therapy." (PMID 19127257, 2009). "Thus, measurements of pretreatment levels of MGMT in melanoma did not predict for response to temozolomide." (PMID 9820180, 1998). "vMF alone could not decrease the MGMT protein in melanoma cells." (PMID 39873425, 2025). "Meanwhile, MGMT transcriptional activity also decreased correspondingly after the use of the ERK inhibitor U0126, suggesting that TMZ may promote the transcription of MGMT by regulating related transcription factors via activation of the ERK pathway in malignant melanoma cells." (PMID 39873425, 2025). "Additionally, with the depletion of MGMT, A375 acquired a more significant increase in sensitivity to DTIC than SK-MEL-28 did, implying that aside from MGMT, other factors were involved in DTIC resistance and may participate in the PA-mediated synergistic effects in melanoma cells." (PMID 37024907, 2023). "IGF-1Ri sensitized BRAF wild-type and mutant melanoma cells to TMZ in vitro, an effect that was independent of MGMT." (PMID 26497996, 2015). "Acral melanomas exhibited differential methylation at the gene bodies of MGMT (4% hypomethylation in acral melanoma group, P = 7e − 3) and TERT (9% hypermethylation in acral melanoma group, P < 1e − 3) compared to nonacral tumors." (PMID 26106605, 2015). "In tumors, five genes (KIT, MGMT, MITF, TERT, and TNF) exhibited methylation levels significantly different between tumor groups including acral compared to nonacral melanomas and matched primary lesions and metastases." (PMID 26106605, 2015). "Comparing the apoptotic response of different melanoma cell lines, one cell line (designated MZ7) was highly resistant to TMZ and did not undergo apoptosis (left panel for a time-course experiment), although these cells did not express MGMT." (PMID 19127257, 2009). "However, despite upregulated MGMT expression, the resistant mechanism was independent of MGMT, and the cells that acquired TMZ resistance showed increased NLRP1 inflammasome activation, NF-κB activity, and IL-1β secretion, which contributed to the melanoma cells’ resistance to TMZ." (PMID 32899791, 2020).